TREM1 (triggering receptor expressed on myeloid cells 1)
Diseases named in the same sentence as TREM1 in open-access papers (continued):
Sharing a sentence is not in itself a finding about the gene and the disease.
tumor (continued). "In clinical sample analysis, we found that the level of TREM-1 on tumor tissue-macrophage is statistically lower than that on corresponding adjacent lung tissue-macrophage or blood monocytes." (PMID 27244892, 2016). "The tumor-bearing mouse model further confirmed that the expression of TREM-1 on TAMs was significantly decreased with tumor growth." (PMID 27244892, 2016). "As an amplifier of immune responses, TREM-1 should be considered as an anti-tumor molecule during tumorigenesis and tumor development." (PMID 27244892, 2016). "whereas the TREM-1 levels on macrophage from spleen exhibited an alternation with opposite direction and significantly increased with tumor growth." (PMID 27244892, 2016). "Comparative analysis indicated that TREM-1 levels on macrophage from tumor tissue samples were significantly higher than those from spleen samples in early stage (at the 8th and the 13th day after tumor-bearing) of tumor progression." (PMID 27244892, 2016). "We found that the expression levels of TREM-1 on monocytes/macrophages in tumor microenvironment are significantly lower than those in periphery." (PMID 27244892, 2016). "TREM-1 mRNA levels of aCP and pCP cells were compared by quantitative reverse transcription-polymerase chain reaction (qRT-PCR) from a collection of native tumor samples comprising 6 pCP and 6 aCP cultured cells." (PMID 27409178, 2016). "Based on the previous data, TREM-1 should to be an anti-tumor molecule through enhancing immune responses." (PMID 27244892, 2016). "In LLC-tumor bearing mouse model, we further investigated the dynamic expression feature of TREM-1 on macrophage with tumor growth." (PMID 27244892, 2016). "We found that the levels of TREM-1 on tumor tissue-derived macrophage gradually decreased with tumor growth." (PMID 27244892, 2016). "The dynamic expression of TREM-1 was detected on CD11b+F4/80+ macrophage isolated from spleen and tumor tissues by flow cytometer." (PMID 27244892, 2016). "Together, these data confirm that tumor cells can induce expression of TREM-1 message and protein in macrophages." (PMID 24842612, 2014). "Co-culture of tumor cells with macrophages led to an induction of TREM-1 as determined FACS analysis." (PMID 24842612, 2014). "Further studies to define the role of TREM-1 in tumor immunomodulation in tumor microenvironment are needed." (PMID 24842612, 2014). "Studies with COX-2 inhibitors and siCOX-2 showed that expression of TREM-1 in macrophages in tumor microenvironment is dependent on COX-2 signaling." (PMID 24842612, 2014). "We next wanted to investigate the mechanism by which tumor cells induce the expression of TREM-1 in macrophages." (PMID 24842612, 2014). "We found abundant macrophages in the stroma of the tumor tissue which showed both TREM-1 and CD68 expressions." (PMID 24842612, 2014). "Our study convincingly shows that TREM-1 is expressed in human NSCLC tissue and that the expression is selectively seen in the tumor associated macrophages in the cancer stroma." (PMID 24842612, 2014). "Ongoing and future studies will establish the role of TREM-1 in tumor growth and define the mechanisms by which TREM-1 modulates tumor growth." (PMID 24842612, 2014). "Future studies will define the detailed mechanisms and signaling pathways employed by PGE2 in tumor microenvironment which are responsible for the expression of TREM-1 in TAMs." (PMID 24842612, 2014). "We assessed the effect of TREM-1 activation on tumor growth in the Pan02 mouse model of PDAC." (PMID 40917508, 2025).
tumor (continued). "In addition to bioinformatics analysis of the heterogeneity of the immune microenvironment between patients in two risk groups, our present work also investigated the impact of TREM1 on key cell populations in the tumor tissue of a xenograft model." (PMID 40551711, 2025). "Additionally, TREM1 expression increased with tumor stage, with stage 4 showing the highest expression." (PMID 40677705, 2025). "Current studies have found the immunomodulatory role of TREM1 in tumor microenvironment." (PMID 39744496, 2025). "We speculated that the expression of TREM1 in OV may promote tumor progression by altering the phenotype of TAMs." (PMID 39744496, 2025). "TREM1 abrogation disrupts these processes, thereby impairing overall tumor cell viability." (PMID 40677705, 2025). "The results showed that the expression of TREM1 was significantly high-expressed in tumor tissues." (PMID 39744496, 2025). "Additionally, ESTIMATE and CIBERSORT analyses were used to assess the correlation between TREM1 and tumor microenvironment." (PMID 39744496, 2025). "The results revealed that TREM1 was highly expressed in tumor samples across multiple cancer types." (PMID 41413734, 2025). "In vitro experiments demonstrated that targeted inhibition of TREM1 not only exerted anti-tumor effects but also suppressed the PMT process in GBM and inhibited the activation of the TLR4/PI3K/AKT/mTOR signaling axis, further highlighting its clinical significance in GBM progression." (PMID 41394801, 2025). "We hypothesize that TREM1 plays a critical role in maintaining the stemness of this subpopulation of LCSLCs and its inhibition can specifically target these cells to restrict tumor proliferation." (PMID 40677705, 2025). "This reduction in LCSLC populations upon TREM1 inhibition suggests that targeting TREM1 could reduce the likelihood of tumor recurrence." (PMID 40677705, 2025). "Notably, co-culture with TREM1+ MDSCs and tumor cells resulted in more pronounced inhibition of T cell function, confirming that MDSCs exerted their suppressive effects via TREM1." (PMID 41413734, 2025). "Moreover, CellChat analysis showed that TREM1+ PMN-MDSCs remodeled the tumor microenvironment through interactions with diverse cellular components." (PMID 41413734, 2025). "However, further in-depth studies are required to fully elucidate the intricate mechanisms of TREM1-mediated signaling between TAMs and tumor cells." (PMID 41394801, 2025). "In general, these findings indicate that TREM1 may act as a tumor suppressor in the immune microenvironment, which increase the infiltration levels of tumor-associated macrophages (TAMs) and Tregs and induce immune-suppression state." (PMID 39744496, 2025). "Furthermore, multiplex immunofluorescence (mIF) experiments demonstrated that TREM1+ PMN-MDSCs exhibited significantly higher distribution in tumor regions compared to non-tumor tissues." (PMID 41413734, 2025). "We confirmed that the delayed tumor growth was TREM-1-dependent using Trem1−/− mice." (PMID 40917508, 2025). "Elevated TREM1 expression in HCC, is associated with enhanced tumor progression." (PMID 40764998, 2025). "Furthermore, genes in our model such as MUC5B and TREM1 have been documented in relevant literature for their roles in the tumor immune microenvironment and prognosis, underscoring the model’s multidimensional novelty and clinical applicability." (PMID 40843359, 2025). "Given TREM1’s emerging role in tumor progression and immune escape mechanisms, its modulation by exercise could support improved immune surveillance and enhance responsiveness to immunotherapeutic strategies." (PMID 40881686, 2025). "Targeting TREM1 may therefore represent a promising dual-action therapeutic strategy to disrupt both cancer stem-like cell function and the pro-inflammatory tumor milieu in HCC." (PMID 40677705, 2025). "Notably, low expression levels of HOXB8 and TREM1 significantly correlated with a low tumor recurrence rate." (PMID 38376699, 2024).
tumor (continued). "Specifically, in the context of PCOS, TREM1 activation in the wound microenvironment recruits immune cells like T cells, NK cells, DCs, and macrophages, thereby promoting the activation of anti-tumor immune cells." (PMID 39323470, 2024). "In vitro, inhibition of TREM1 signaling could result in a decrease in tumor-promoting effects of monocytes/TAMs." (PMID 38370418, 2024). "In vitro, inhibition of TREM1 signaling could result in a decrease in tumor-promoting effects of monocytes/TAMs, suggesting that TREM1 might involve in the formation of immunosuppressive microenvironment." (PMID 38370418, 2024). "Importantly, we observed an expansion in proportion of TREM1 myeloid cells in BCC tumors with more abundant BIT tumor epithelium compared to those with less abundant BIT tumor epithelium." (PMID 39289380, 2024). "It was also found that the interaction of Tag7 with TREM-1 leads not only to increased expression of proinflammatory cytokine genes, but also to the generation of subpopulations of lymphocytes with cytotoxic effect on HLA-negative tumor cells." (PMID 38203798, 2024). "Furthermore, ROS formation assays showed that MDSCs isolated from Trem1–/– tumor-bearing mice had significantly decreased ROS formation capabilities compared with Trem1+/+ MDSCs." (PMID 37651197, 2023). "The content of Tregs is also increased in high TREM-1 group, which could produce immunosuppressive cytokines and immune-inhibitory receptors to disturb the activation of anti-tumor T cell responses, leading to a worse prognosis." (PMID 37217993, 2023). "In benign tissues, TREM-1 expression was very low, but high in tumor tissue areas." (PMID 37217993, 2023). "This implies that the role of TREM1 in patient survival might be context-specific and tumor-dependent." (PMID 37651197, 2023). "To test this hypothesis, we compared the immunosuppressive capacity of MDSCs isolated from Trem1+/+ and Trem1–/– tumor-bearing mice." (PMID 37651197, 2023). "Although these hub genes can secrete the release of promote inflammatory factors, affect the tumor microenvironment, only TREM-1 is a cell surface receptor and a member of the immunoglobulin superfamily that potently amplifies inflammatory responses by secretion of proinflammatory mediators." (PMID 37217993, 2023). "In human HCC, TREM-1 truly seems to be involved on tumor cell proliferation and invasion." (PMID 35875168, 2022). "Therefore, our data suggest that cell signaling pathways controlled by HuR dimerization and TREM1 activation are involved in myeloid-derived cell migration toward tumor cells in the hypoxic condition." (PMID 36249290, 2022). "The presence of a TREM-1 or TREM-2 ligand within the tumor milieu would suggest that TREM could directly regulate TAM and/or MDSC at the tumor site." (PMID 35223446, 2021). "Next, we assembled a TREM-1 target gene panel comprising genes significantly induced by TREM-1 activation and associated with intratumoral TREM1+ myeloid cells to serve as an estimator of TREM-1 signaling output in different cell and tumor populations." (PMID 34956864, 2021). "Because of its onset in a lymphoid-rich area, oropharyngeal carcinoma may be a promising model to evaluate the putative role of TREM-1 in the progression and prognosis of the tumour." (PMID 33769181, 2021). "Despite TREM-1 macrophages distributed outside show a strong and significant association with the OS, dendritic cells are rarely represented in the tumours and do not reveal any significance on patients’ outcomes." (PMID 33769181, 2021). "Since they arise in lymphoid-rich areas and intense lymphocytic infiltration has been related to a better prognosis, a TREM-1 putative function in tumour progression and survival has been hypothesized." (PMID 33769181, 2021). "It has also been investigated that TREM1 expression is regulated by NF-κB at the transcriptional level, emphasizing the contribution of NF-κB pathway activation in bridging inflammation and tumor promotion and progression." (PMID 33575478, 2021).
tumor (continued). "Correlation analysis of TREM-1 expression with tumor purity revealed that TREM-1 may influence the immune status of the tumor microenvironment." (PMID 34122331, 2021). "Taken together, our data suggest that manipulation of the TREM-1/TREM-2 balance in tumors may be a novel means to modulate tumor-infiltrating myeloid cell phenotype and function." (PMID 35223446, 2021). "We hypothesized that TREM-1 would be overexpressed on MDSC in tumor-bearing mice and that TREM-2 would be co-expressed on MDSC and TAM in tumor-bearing animals." (PMID 35223446, 2021). "Because the identity of the TREM-1 ligand(s) remains largely unknown, we used anti-TREM-1 to engage the receptor on the surface of PMN-MDSC sorted from spleens of 4T1 tumor-bearing mice." (PMID 35223446, 2021). "Notably, this observation was consistent with our findings in the MC1 and MC2 cohorts where TREM1 expression by bulk tumor analysis was higher in basal-like tumors as compared to luminal tumors." (PMID 34956864, 2021). "Because TREM-1 is widely distributed throughout the body and plays an important role in the inflammatory process, it has attracted great attention in the context of tumor formation, development and metastasis." (PMID 34122331, 2021). "It is tempting to speculate that at the tumor site, as is thought to be the case during sepsis, sTREM-1 may be blocking the function of membrane-bound TREM-1 via its interference with bona fide TREM-1 ligands." (PMID 35223446, 2021). "In addition, TREM1 signaling was shared in splenic Treg from MC38 tumor bearing mouse, and Treg from TC-1 lung tumor." (PMID 34084175, 2021). "Under this scenario, the inhibition of TREM-1 would lead to increased tumor growth." (PMID 32456204, 2020). "This also indicates that the low expression level of TREM-1 in TAMs may affect the pro-inflammatory effect of TAMs, which is beneficial to tumor growth." (PMID 33224886, 2020). "High TREM-1 expression on MPs in mouse and human tumors and/or sTREM-1 release into the biologic fluids of cancer patients were indicated as independent predictors of tumor progression and poor patient prognosis." (PMID 32456204, 2020). "Although speculative, the exaggerated production of these and other mediators through TREM-1 activation may represent the mechanism by which expression of TREM-1 on TAMs can promote tumor growth and progression." (PMID 32684831, 2020). "Following these previous studies, we hypothesized that an increase of NK cell-mediated anti-tumor effect due to ApoE KO could be involved with TREM-1 expression." (PMID 31275318, 2019). "In that case, high TREM-1 expression in TAMs and high levels of sTREM-1 in sera could both indicate, that a tumor micro environment has been established that probably promotes tumor growth and therefore signifies an unfavorable course of the disease." (PMID 30018308, 2018). "The attenuated tumor development in Trem1−/− mice may be considered a consequence of their diminished inflammatory response reported in distinct models of experimental colitis." (PMID 29093489, 2017). "However, besides providing direct evidence for a tumor-promoting role of TREM-1 in vivo, our study reveals two novel findings: First, in the AOM/DSS model of CRC, tumor-infiltrating neutrophils, but not TAMs, represent the major TREM-1-expressing cell subset." (PMID 29093489, 2017). "However, we believe that the effects of TREM-1-activated neutrophils on tumor development are likely multilayered and operative also in established tumors." (PMID 29093489, 2017). "It is currently unclear why the Trem1−/− tumor environment favors an accumulation of B cells." (PMID 29093489, 2017). "Former studies investigating the potential role of TREM-1 in cancer have either correlated the in situ expression of TREM-1 with clinicopathological data, employed in vitro co-cultures of cancer cells with macrophages, or have interfered with TREM-1-mediated signaling using in vivo tumor models." (PMID 29093489, 2017).
tumor (continued). "Indeed, in human non-small cell lung cancer (NSCLC) increased TREM-1+ tumor-associated macrophages (TAMs) were linked with reduced survival, and inhibiting TREM-1 suppressed tumor growth in a mouse xenograft NSCLC model." (PMID 29093489, 2017). "All these evidences indicated that the effects of tumor-bearing on TREM-1 expression might be strikingly different between on periphery circulating monocyte/macrophage and tumor-tissue infiltrating monocyte/macrophage." (PMID 27244892, 2016). "Additionally, in NSCLC patients and tumor-bearing mouse model, our results demonstrated that the expression levels of TREM-1 on monocytes/macrophages were significantly decreased during tumor progression." (PMID 27244892, 2016). "Moreover, along with tumor growth, the levels of TREM-1 gradually decreased on macrophage of tumor tissues." (PMID 27244892, 2016). "We thought a “decreased” level of TREM-1 may offer a more suitable “chronic inflammation-related soil” for tumor growth in tumor microenvironment." (PMID 27244892, 2016). "Notably, further analysis indicated that TREM-1 on tumor tissue-derived monocytes/macrophage was significantly lower compared with that on peripheral blood monocytes from patients with NSCLC." (PMID 27244892, 2016). "We think the different state of immune between periphery (spleen) and tumor microenvironment (tumor tissue) may lead to the difference of TREM-1 expression during tumor progression." (PMID 27244892, 2016). "We found the decreasing level of TREM-1 on TAM with tumor advance by flow cytometry analysis." (PMID 27244892, 2016). "The levels of TREM-1 were remarkably decreased during tumor progression." (PMID 27244892, 2016). "Interestingly, our results demonstrated that TREM-1 levels gradually increased on spleen macrophage with tumor growth, which is an opposite trend in periphery during tumor progression." (PMID 27244892, 2016). "All these results indicated that TREM-1 expression showed a dynamic alternation on macrophage during tumor progression, suggesting that the expression levels of TREM-1 might be a novel characteristic for evaluating macrophage state in tumor microenvironment." (PMID 27244892, 2016). "Besides, IL-1β, IP-10, M-CSF and TREM-1 levels in tumor tissues were also enhanced by LNT, further confirming the activated immune responses by LNT in mice." (PMID 27353254, 2016). "Thus, we want to reveal the expression and functions of TAM-related TREM-1 in tumor microenvironment." (PMID 27244892, 2016). "Similarly, Sigalov also designed a ligand-independent peptide-based TREM-1 (triggering receptor expressed on myeloid cells-1) inhibitor to specifically silence TREM-1, and this peptide delayed tumor growth in xenograft models of human NSCLC." (PMID 26568964, 2015). "From these six genes two were higher expressed in GAMs derived from the RCAS model (CD300lf and Cd200r4), two genes were expressed at similar levels in GAMs in both tumor models (Trem1 and Sh2d1b1), and two genes were higher expressed in GAMs derived from the GL261 model (Uck2 and Creb5)." (PMID 25658639, 2015). "Interestingly, elevated serum cytokines important in myeloid differentiation were found in Rip2-deficient tumor bearing animals, with increased levels of G-CSF and M-CSF, as well as MCP-1 and TREM-1." (PMID 24733360, 2014). "Our study suggests that TREM-1 inhibition may prove to be an adjunctive therapy to limit tumor growth." (PMID 24842612, 2014). "Although speculative the exaggerated production of these mediators by TREM-1 may be a mechanism by which TREM-1 expression in TAMS can promote tumor growth and progression." (PMID 24842612, 2014). "We therefore hypothesized that expression of TREM-1 in TAMS might be induced by PGE2 production from tumor cells via cyclo-oxygenase pathway." (PMID 24842612, 2014).